IL6 (interleukin 6)
Diseases named in the same sentence as IL6 in open-access papers (continued):
Sharing a sentence is not in itself a finding about the gene and the disease.
tumor (continued). "Furthermore, inflammation fosters an environment suitable for tumor growth by releasing specific cytokines, such as IL-6 and TNF-α, and growth factors like vascular endothelial growth factor (VEGF), which enhance cell proliferation and aid in tumor nourishment through angiogenesis." (PMID 38474160, 2024). "IL-6 has been shown to inhibit the differentiation of T cells into Th1 cells, which are central to specific cytotoxic anti-tumor immunity; and to promote the differentiation of CD4 + T cells into Th2 and Th17 cells, which are less effective at controlling tumor growth." (PMID 38689325, 2024). "For instance, proinflammatory cytokines such as interleukin-6 (IL-6) and tumor necrosis factor-alpha (TNF-α), released by T lymphocytes and activated macrophages, can stimulate cancer cells and stromal cells to produce other factors that enhance tumor survival, proliferation, and angiogenesis." (PMID 38539448, 2024). "The present study demonstrated that ART1 knockdown significantly inhibited IL-6-induced p-STAT3 and its target proteins, c-Myc, cyclin D1 and Bcl-xL (amp and E, 3 A-D, 7D & E), the proliferation of CRC cells and the growth of transplanted tumours in a mouse model." (PMID 38504172, 2024). "In TME, IL‐6 and CCL2 trigger autophagy, respectively, by binding to interleukin 6 receptor (IL‐6R) and CC chemokine receptor 2 (CCR2) and induce macrophage towards M2 type, which is strong support for maintaining inhibitory TIME and promoting tumour progression." (PMID 38652105, 2024). "Similarly, IL-6 levels tended to be increased by the tumor secretome of non-cachectic patients (1.6-fold, p = 0.14) but not by that of the cachectic patients." (PMID 38339292, 2024). "In addition, IL-6 secreted by polarized TAMs enhances the phosphorylation of PGK1 in tumor cells and activates PGK1, demonstrating a novel mechanism by which macrophages promote tumor growth by regulating glucose metabolism." (PMID 39594816, 2024). "IL10 promotes differentiation of Tregs, enhances tumor cell survival, proliferation, and metastasis by controlling antitumor immunity mostly through the STAT3 signaling pathway via the IL10 receptor (IL10R), whereas IL6 activates Th2 cells to promote tumor progression." (PMID 38592450, 2024). "In the human PDAC patient tumor transcriptome (TCGA), we identify strong and significant correlations between tumoral GHR expression and known lymphangiogenic (LYVE1, FLT4, VEGFC, and PDPN) and angiogenic (PDGFRa, FGFR1, TGFB3, TGFB1, TGFBR2, HIF1a, IL6, and IL1B) markers." (PMID 39000545, 2024). "IL-6 and IL-8 in turn might induce ATX expression in ADSC in the tumor microenvironment." (PMID 39338222, 2024). "Cytokines produced by CAFs, including IL-6, VEGF, IL-8, HGF, and SDF-1, have been identified; therefore, we hypothesized that in CRC, the humoral factors produced by CAFs also promoted the migration of monocytes into the tumor." (PMID 39000110, 2024). "However, as a bioenergetic drug, its effects on metabolic coupling markers (Cav1, MCT4) and the factors involved in tumor-fibroblast interactions (IL-6, TGFβ, and acid lactic) are not thoroughly and simultaneously examined." (PMID 38361760, 2024). "Similarly, high IL-6 has been shown to be a poor prognostic marker to ICI response in multiple tumor cohorts, and preclinical data suggest a potential dual benefit of IL-6 blockade, including improved tumor control and reduced toxicity." (PMID 39403935, 2024). "Moreover, STAT3 may promote tumor progression by modulating the immune response within tumor microenvironments through several signaling pathways, including S1PR1, JAK, and IL-6." (PMID 39738726, 2024). "In addition, many predictive biomarkers are based on immune cells or inflammatory cytokines, such as NLR, PLR, LMR, PD-1+ granulocyte percentage, SII, monocyte index, TGF-β, IL-6, and CRP, reflecting the clinical implication of tumor immune microenvironment in the efficacy of ICI therapy for HCC." (PMID 38169551, 2024).
tumor (continued). "Immunohistochemical analysis results of tumor tissues also showed that the expression of EMT pathway components was significantly activated after IL-6 overexpression, and these effects were eliminated after IL-6 knockdown or treatment with an IL-6 neutralizing antibody." (PMID 38424624, 2024). "IL-6 potentiates angiogenesis in PC by increasing the expression of VEGF on mesothelial cells, along with stimulating proliferation and migration of endothelial cells, which may contribute to angiogenesis in the tumor microenvironment." (PMID 38689325, 2024). "This suggests that the majority of potential PCNSL biomarkers, including cytokines (IL-6, IL-10) and soluble receptor proteins, may not stem directly from the tumor tissue." (PMID 39144147, 2024). "The other lineage is the IL-1-responsive inflammatory CAF population, located distal to tumor nests in a desmoplastic area, coding for increased Jak/STAT signaling pathway members, interleukins, chemokines, and cytokines such as Cxcl1, 2, or 3, IL-6, IL-11, IL-21 and Lif." (PMID 37046676, 2023). "We also did not have CRP levels in cohort 2 to correlate these with IL-6 expression on the tumor." (PMID 37852738, 2023). "Furthermore, the absolute numbers of CD3+, CD4+ and CD8+ T cells in the anti-IL-6 treatment and cryo-thermal therapy groups were not significantly different from those in the tumor-bearing group." (PMID 37108179, 2023). "In addition, ovarian cancer ascites derived primary stem cells promote tumor progression by interacting with the cancer cells and macrophages to produce pro-angiogenic factors such as vascular endothelial growth factor (VEGF) and IL6." (PMID 36698173, 2023). "Therefore, cryo-thermal therapy in conjunction with anti-IL-6 treatment in highly aggressive and MDSC-dominated immunosuppressive tumor model could attain a superior therapeutic outcome." (PMID 37108179, 2023). "Notably, levels of IL-6 and TNF-α were increased in lungs from 4T1.2-Luc2 tumor-bearing mice." (PMID 38033489, 2023). "On the one hand, neutrophil promotes angiogenesis and progression of tumors through secreting tumor growth promoting factors, such as vascular endothelial growth factor (VEGF), matrix metalloproteinase, hepatocyte growth factor (HGF), interleukin 6 (IL-6) and IL-8." (PMID 37072770, 2023). "Similarly, other factors released by tumor cells, such as the platelet-derived growth factor (PDGF) and fibroblast growth factor 2 (FGF-2), or inflammatory signals such as interleukin (IL)-1, IL-6 and tumor necrosis factor alpha (TNF-α), recruit and proliferate additional CAFs." (PMID 37173977, 2023). "Indeed, in murine tumor models, treatment combined with ICI and IL-6 blockade was reported to lead to increased tumor shrinkage in vivo, with a higher density of CD4+/CD8+ effector T cells and reduction of Th17, macrophages, and myeloid cells within tumor tissues." (PMID 38469154, 2023). "In addition, IL-6 was detected in MDCS, and the IL-6R-neutralizing antibody inhibited both STAT3 activation and tumor proliferation induced by MDCS stimulation in both tumor cell lines." (PMID 36961655, 2023). "Il11, Il6, Ccl11, Mdk and Ptn have also been shown to play key roles in cancer progression and immune modulation, suggesting that altered expression of these genes in KPC-Cdh11+/- mice may contribute to changes in tumor immune profile." (PMID 37954069, 2023). "Specifically, we experimentally determined whether Wnt/β-catenin and IL6-JAK-STAT3 signal pathways were activated in ccRCC by examining the expression of TTC13, β-catenin, JAK2, p-STAT3, STAT3 and p-JAK2 in ccRCC tumor tissues as well as the adjacent normal tissues." (PMID 37927783, 2023). "In the later stage of treatment, high dosages of sorafenib could continuously induce the downregulation of IL-6 expression and the upregulation of HIF-1α expression, thereby continuing to downregulate the expression of PFKFB3 and inhibiting tumor growth and invasiveness." (PMID 37476196, 2023).
tumor (continued). "The tumor-promoting microenvironment is generated by stimulating angiogenesis (activation of PI3K pathway via VEGF and EGF), regulating adhesion (changes in composition of integrins), and inflammation (pro-inflammatory cytokines IL6 and IL8 and increased neutrophil to lymphocyte ratio)." (PMID 37445860, 2023). "Inflammatory responses occur at the early stage after LITs, increasing the permeability of tumor vessels and promoting the injured tumor cells to produce chemokines (e.g., CCL2, CCL3, CCL4, CCL8, etc.)and proinflammatory cytokines (e.g., TNF-α, IL-1, IL-6, IL-17, etc.)." (PMID 36831664, 2023). "However, both IL-6 and IL-1β levels were still elevated in the RT and COMB groups, which might have resulted in the higher cleaved caspase-3 level and better tumor inhibition seen in these two groups." (PMID 37242761, 2023). "Furthermore, the results of DEGs and HALLMARK GSEA analysis showed that the FAP high expression was significantly correlated with EMT, cell junction, IL-6/STAT3, and TGF-β signaling pathway and chemokine releasing, which further suggests its immune suppressive role and close interaction with tumor." (PMID 37046312, 2023). "Moreover, it may be of great significance to further investigate the possible coaction between the IL‐6/STAT3 signaling pathway and tumor immune efficacy in patients with HCC." (PMID 36951443, 2023). "Similar results were obtained in vivo where the elevated expression of IL-6 (approximately twofold), IL-1β (threefold), and TNF-(sixfold) was observed (the expression of the stated inflammatory markers was evaluated in XM-S and XM-R mouse models after 21 days of tumor induction)." (PMID 36840009, 2023). "The elevated neutrophil-to-lymphocyte ratio in the TME during neoadjuvant chemotherapy could impair its anti-tumor efficacy due to upregulated neutrophil-CAFs-tumor cell IL-1β/IL-6/STAT-3 signaling, showing a poor/absent response." (PMID 37173915, 2023). "Thus, Ccne1 seems to be involved in the control of Il6 expression in the fibrotic and tumorous liver independent of Tnf." (PMID 37620309, 2023). "Several in vivo studies have shown that the IL-6 knockdown could attenuate tumor metastasis in mice models, while IL-6 over-expression has also been validated with enhancing head and neck tumor growth and EMT change, eventually leading to tumor metastasis to the lung site." (PMID 37047623, 2023). "Pancreatic Reck deletion was found to result in the emergence of αSMA-low/IL-6–high mesenchymal (vimentin-positive) CAF-like cells via EMT of PDAC cells, which share a similar expression pattern of marker proteins with a tumor-promoting type of CAF, termed inflammatory CAF (iCAF)." (PMID 37712427, 2023). "Concomitantly, a sandwich ELIZA for pro-inflammatory cytokines (TNF-α, IL-1β, IL-6 and IL-12) revealed a dose-dependent reduction in levels of pro-inflammatory cytokines (p<0.05 and p<0.001) of ART-treated tumor-bearing mice compared to the untreated tumor-bearing mice." (PMID 38144525, 2023). "In addition, non-responsive tumor EC-derived IL-6 is a cytokine that encourages macrophage M2-like polarisation in the tumor microenvironment." (PMID 37056346, 2023). "We found that high DCLK1 and IL-6 expression predicted shorter relapse-free survival (RFS) in TNBC (n = 392) but not in luminal A (n = 522), luminal B (n = 332) and HER2 (n = 315) subtypes, which suggested the dominant roles of DCLK1 and IL-6 in TNBC tumor recurrence." (PMID 37069669, 2023). "While chronic inflammation promotes tumor progression, tumor cells themselves also attract immune cells via chemokines such as IL-8, CCL2 (MCP-1), CCL3 (MIP-1α), CCL5 (RANTES), CXCL6 (huGCP-2), and cytokines such as IL-1β, IL-6, TNFα, GM-CSF, and G-CSF, inducing inflammation." (PMID 36614196, 2023).
tumor (continued). "CAFs secrete soluble factors, which include cytokines, chemokines, and growth factors such as interleukin 6 (IL-6), C-type lectin domain family 3 member B (CLEC3B), C-X-C motif chemokine 12 (CXCL12), and epidermal growth factor (EGF) to transform the TME to support tumor growth." (PMID 37469395, 2023). "Therefore, specific inhibition of IL-6 trans-signaling, rather than total inhibition of IL-6 signaling, is sufficient to blunt tumor initiation and impair tumor progression without compromising IL-6 classic signaling-driven protective immune responses." (PMID 37480115, 2023). "Cancer-associated fibroblasts (CAFs) are responsible for a dense fibrotic tumor stroma, and an increased expression of GPR68 could be shown in CAFs, resulting in enhanced interleukin-6 (IL-6) expression via a cAMP/PKA/cAMP response element-binding protein signaling pathway." (PMID 36902589, 2023). "An anti-IL-6 antibody or lentiviral-mediated RNAi against IL-6 in MSCs, the inhibition or knockdown of ET-1 in cancer cells, or the suppression of ERK and Akt in host endothelium cells can all be used to target the IL-6/ET-1/Akt or ERK pathway of tumor-stroma interaction." (PMID 38022534, 2023). "Therefore, targeting the IL6-JAK-STAT3 pathway and IFN-α response may inhibit tumor proliferation and activate the antitumor immune response to benefit patients with radioresistant CC." (PMID 36867313, 2023). "Interestingly, UA could dose-dependently weaken the increased spleen weight in LLC tumor-bearing mice at concentrations within 200 mg/kg, and the cytokines IL-6, IL-1β, and TNF-α are produced by immune cells or tumor cells." (PMID 37190306, 2023). "In TME or TIME infiltrated B cells under the influence of IL-6, IL-1β, IL-12p35, and low oxygen (tumor-promoting molecules), which polarize to regulatory B cells (Bregs), producing TGF-β, granzyme B (GZMB), IL-10, and IL-35, which promote tumor growth and metastasis." (PMID 37275901, 2023). "Interestingly, IL6 is known to promote tumor growth by upregulating antiapoptotic and angiogenic proteins in tumor cells, and elevated IL10 may inhibit tumor growth by suppressing IL6 production." (PMID 37238004, 2023). "Moreover, in the tumour microenvironment, C118P may indirectly affect ASCT2 expression through IL-6 and receptor gp130." (PMID 37894450, 2023). "The main mediators of tumor‐induced polarization of macrophages from M1 to M2 types are chemokines and cytokines, such as prostaglandin E (PGE) 2, milk fat globule‐E8 (MFG‐E8), granulocyte/macrophage colony‐stimulating factor (GM‐CSF), CSF‐1, CCL5, IL‐4, IL‐6, and TGF‐β." (PMID 37937304, 2023). "They home into the tumor site, following secretion of soluble factors, such as IL-6, IL-1β, and/or transforming growth factor-β1 (TGF-β1) by tumor cells, as well as the stromal cell-derived factor1α (SDF-1α) by stromal cells that promote paracrine signaling in tumor cells." (PMID 37175439, 2023). "We hypothesize that a higher concentration of IL-6 encourages M1 to M2 transformation of macrophages in TME, increases the recruitment of macrophages at tumor sites, and further activates the feedback loop between IL-6 and M2 to promote tumor growth and survival." (PMID 37124547, 2023). "In addition, cytokines TNF-α, IL-6, IL-1β, and IFN-γ are involved in the adhesion of circulating MSCs to the vascular endothelial layer, and MSCs adhering to the vascular endothelial layer enter tumor tissue through the vascular wall." (PMID 37666813, 2023). "Therefore, both IL-6 and TNFR2 may contribute to the tumour-promoting roles of STAT3, hence targeting the IL-6-signaling pathway may help to decrease maximally suppressive TNFR2+ Tregs." (PMID 36765633, 2023). "Inflammation-related cytokines, such as interleukin-6 (IL-6) and C-reactive protein (CRP), as well as changes in metabolism-related adipokines, such as adiponectin and leptin, have been shown to reflect a proinflammatory microenvironment that promotes tumor development and progression." (PMID 36670988, 2023).
tumor (continued). "In this study, the authors discovered that sorafenib’s anti-tumor effects were increased in a mouse model of HCC by targeting the IL-6/JAK2/STAT3 signaling pathway with an IL-6 neutralizing antibody, implying that IL-6 may contribute to HCC patients’ resistance to sorafenib therapy." (PMID 37892997, 2023). "Type II inflammation, mediated by IL-11, IL-22, IL-33, IL-6/membrane IL-6 receptor α (mIL-6 Rα) and cell-mediated immune response through CD4+ Th2 cells, which produce IL-12, M2 macrophages, and group 2 innate lymphoid cells (ILC-2), induces classic anti-inflammatory signaling and tumor relapse." (PMID 37296983, 2023). "IL6 and other observed pro-inflammatory cytokines as well as the proangiogenic factor VEGF are involved in STAT3-regulated pathways and thus might contribute to tumor growth induction." (PMID 35841421, 2023). "However, there is a controversy on this point as several other studies reported that inhibition, not activation, of the IL-6/STAT3 signalling pathway induced cellular senescence in tumour cells." (PMID 36825563, 2023). "In a mouse model, a minimally invasive procedure to remove human triple-negative cell line-generated xenograft tumors eliminated tumor-secreted factors, including IL-6, IL-8, VEGF, EGF, PDGF-AA, MIF, SerpinE1, M-CSF, focal adhesion, metalloprotease and apoptosis regulation processes." (PMID 37296983, 2023). "More importantly, since IL-6 transcription can be triggered by inflammatory cytokines including TGFβ, IL-1, and TNFα which are also activated mainly by NF-κB and STAT3, IL-6 within the BM microenvironment can create a feed-forward loop to propagate tumour progression." (PMID 37808081, 2023). "Here, we show that the Kindlin-1-dependent regulation of IL-6 secretion controls the differentiation of CD4+ T cells into FoxP3+ Tregs and the ability of Tregs to suppress CD8+ T cell proliferation in vitro, while also regulating Treg numbers in the tumor microenvironment." (PMID 36883731, 2023). "MSCs can secrete IL‐6 in OS cells and promote their migration and invasiveness through the production of phosphorylated STAT3, suggesting that MSCs in the normal bone tissue surrounding the OS tissue can undergo OS metastasis and inhibit apoptosis of tumor cells through the STAT3 pathway." (PMID 37441462, 2023). "Although the Kindlin-1-dependent regulation of IL-6 secretion from the Met-1 tumor cells was able to able to regulate Treg infiltration and the function of the cytotoxic T cells in vivo this was not sufficient to induce tumor clearance." (PMID 36883731, 2023). "Interestingly, we demonstrated that DHEA educated TAMs in a less aggressive phenotype, reducing the gene expression of several markers of TAM phenotype, including IL-6, MMP-9, VEGF, IL-10, and MPC-1, which sustain tumor invasiveness, angiogenesis, and metastasis." (PMID 36765778, 2023). "CAFs promote tumor development by providing the cells of the TME with the necessary signals to proliferate and enhance angiogenesis, through the overexpression of NF-kB, IL-6, cyclooxygenase-2 (Cox-2), and CXCL1, molecules known to have pro-tumorigenic activity." (PMID 37168385, 2023). "Numerous studies have shown that the MYC-dependent pathway in tumor cells can indirectly affect the expression of cytokines in the TIME, such as the reduction in the expression of interleukin-2 (IL-2), interferon-γ (IFN-γ), and perforin and the increase in the expression of interleukin-6 (IL-6)." (PMID 36966168, 2023). "Generally, circulating IL-6 levels were found to correlate with systemic inflammatory responses in CRC patients undergoing surgery, and it has broad functions in CRC development, such as in promoting tumor growth, spreading, and angiogenesis, as well as in regulating treatment resistance." (PMID 37194025, 2023).